INS (insulin)
Diseases named in the same sentence as INS in open-access papers (continued):
Sharing a sentence is not in itself a finding about the gene and the disease.
Obesity (continued). "For instance, it was found that the overproduction or administration of adropin enhances insulin sensitivity, attenuates hepatic steatosis and delays the development of obesity in mice fed a diet enriched in fat." (PMID 34199277, 2021). "In summary, we show for the first time that short-term, but not acute intake, of NZBC extract improves postprandial glucose handling and whole-body insulin sensitivity in individuals with overweight or obesity." (PMID 32648022, 2021). "Anthropometric parameters, levels of serum analytes related to obesity and Ins-R, and the esophageal insulin/IGF-1 signaling pathway were analyzed." (PMID 34684639, 2021). "Adiponectin is the most abundant adipokine that exerts insulin-sensitizing actions in obesity-related metabolic disorders." (PMID 33567531, 2021). "ADSC-derived exosomes mitigated diet-induced obesity and improved glucose tolerance and insulin sensitivity." (PMID 33816504, 2021). "For example, FASN is a gene encoding for a fatty acid synthase and is known to play a key role in the regulation of obesity; an increased FASN expression was associated with an impaired insulin sensitivity." (PMID 32709145, 2020). "Zhu L., Martinez M.N., Emfinger C.H., Palmisano B.T., Stafford J.M.Estrogen signaling prevents diet-induced hepatic insulin resistancein male mice with obesity." (PMID 33659826, 2020). "Increased energy expenditure and decreased energy consumption are the most recommended lifestyle changes to reduce obesity and increase insulin sensitivity in the treatment of dietary obesity (DIO) and obesity-related disease." (PMID 32366215, 2020). "IR is a condition in which cells fail to respond normally to insulin, and characterized by a set of signs comprising obesity, increased blood sugar, dyslipidemia, and elevated blood pressure." (PMID 32998739, 2020). "In 2008, Patsouris and colleagues demonstrated that the ablation of CD11c+ cells during obesity restored insulin sensitivity by decreasing inflammatory markers." (PMID 32140136, 2020). "The concentrations of plasma MaR1 correlated closely with multiple clinical parameters involving obesity, glucose and lipid metabolism disorders, and insulin secretion and resistance." (PMID 32377160, 2020). "Intentional weight loss remains the cornerstone therapy to improve insulin sensitivity and in some circumstances to prevent the incidence of T2DM in individuals with obesity and prediabetes." (PMID 32872570, 2020). "Alterations in α7nAChR levels and activation are relevant to other aspects of obesity, including in modulating the effects of central insulin on hepatic gluconeogenesis." (PMID 32260529, 2020). "The carbohydrate-insulin model of obesity focuses on the endocrine and metabolic effects of food and has been garnering interest recently." (PMID 31846028, 2020). "In animal models, it had also been demonstrated that a high-salt diet can lead to endogenous fructose production, leptin resistance and excessive appetite, and can lead to obesity, insulin resistance and fatty liver." (PMID 32411541, 2020). "Persistent obesity dysregulates metabolic processes, including action of insulin on glucose-lipid-free fatty acid metabolism, and severely affects processes controlling blood glucose, blood pressure and lipids." (PMID 32164195, 2020). "While ROS is needed as a secondary messenger of insulin signaling and vascular contractility, obesity-related oxidative stress can trigger the pathophysiology of the related cardiovascular diseases." (PMID 32630640, 2020). "Leptin in serum is elevated in the case of obesity as it functions to accelerate energy expenditure, whereas insulin levels are negatively correlated with adiponectin levels in 3T3-L1 preadipocytes." (PMID 33425000, 2020). "The intestinal-insulin axis formed by the host and microbiota during symbiotic evolution regulates the insulin level, which confirmed that there is a close relationship between microorganism and host in the course of obesity-T2DM." (PMID 32920548, 2020).
Obesity (continued). "Depletion of the microbiota, germ-free condition or co-housing with wild type mice was sufficient to restrain inflammation, obesity, and insulin tolerance in knock out mice, highlighting a direct link of the gut microbiota in obesity and inflammation." (PMID 33178196, 2020). "Various effects of FXN on obesity parameters have been observed with regard to body weight, visceral fat, adipose tissue size, fasting blood glucose concentrations, plasma insulin levels, and lipid and cholesterol metabolism rates, among others." (PMID 32260306, 2020). "A total of 44 protein spots (26 unique proteins) were found to be significantly altered in patients with T2D and/or obesity versus lean individuals in either the basal state or after insulin administration." (PMID 32731645, 2020). "For example, preclinical evidence from male C57BL/6 mice shows that insulin levels are elevated several weeks prior to the onset of obesity." (PMID 32326226, 2020). "Leptin, which has a similar action in obesity to that of insulin in diabetes, is a hormone that responds to fat deposition." (PMID 32906753, 2020). "Such a burst in obesity prevalence can, in part, be attributed to lifestyle and to higher doses of insulin, however obesity is also highly heritable." (PMID 32635923, 2020). "A link between obesity and impairment of the insulin-signaling pathway was demonstrated in a study where of mice given a high-fat diet during pregnancy resulted in offspring with both increment in body mass and adiposity also had lower levels of IRS1." (PMID 32574162, 2020). "At puberty, insulin secretion increases physiologically but the rise is higher in adolescents with obesity who develop mild to severe hyperinsulinemia." (PMID 32390939, 2020). "IP6K3 knockout mice showed decreased body weight, fat mass, blood glucose, blood insulin, plasma lactate, and increased glucose tolerance from age induced obesity." (PMID 33139672, 2020). "By comparison, these data indicate that muscle ceramides are likely to be elevated and related to insulin sensitivity during metabolic disturbances such as obesity and T2DM." (PMID 32098447, 2020). "For instance, in obesity, macrophages secrete proinflammatory cytokines, tumour necrosis factor alpha (TNFα), and interleukin-6 (IL-6) that impairs insulin signalling." (PMID 32566678, 2020). "Specifically, hypothalamic inflammation in obesity is thought to contribute to impaired action of leptin, insulin, and other hormones." (PMID 32993686, 2020). "HFD induces obesity in Nlrp3 global knockout mice but prevents the development of adipose tissue inflammation and insulin resistance." (PMID 33379163, 2020). "In obesity, it has been reported that adiponectin protects liver from steatosis and inflammation: it increases the capacity of insulin to suppress glucose production." (PMID 32718097, 2020). "Together with the obesity epidemic, type II diabetes (T2D), which is a result of the body’s ineffective use of insulin due to inadequate insulin secretion by pancreatic β cells, has become a public health challenge in many countries." (PMID 32235611, 2020). "In conclusion, this study demonstrated that chrysophanol can activate brown fat through the SIRT6/AMPK pathway and increase energy consumption, insulin sensitivity, and heat production, thereby alleviating obesity and metabolic disorders." (PMID 33274005, 2020). "Incidence rates of AF were higher for subjects with high bodyweight variability in all subgroups by age strata, sex, presence of obesity, hypertension, or chronic kidney disease, number of oral anti-diabetic medication, insulin use, and DM duration." (PMID 32534567, 2020). "To confirm the improved effect of Tan I on glucose metabolism and insulin sensitivity by the prevention of obesity, we performed glucose and insulin tolerance tests in mice." (PMID 32349456, 2020).
Obesity (continued). "β-cell proliferation is the primary method by which β-cell mass increases during diet-induced obesity, stimulated by increased blood insulin and glucose concentrations." (PMID 33604590, 2020). "Mimicking OSA in rodents by exposing animals to repetitive hypoxia/reoxygenation cycles confirms the causal link between CIH, systemic insulin resistance and insulin signaling alterations in white adipose tissue (WAT), independently of obesity." (PMID 33324235, 2020). "In summary, our data suggest that NOD2 activation alleviates the insulin resistance, pancreatic dysfunction and restricts the obesity-induced T2D onset." (PMID 32774333, 2020). "The effects of catch-up fat are remarkable and frequently derived in obesity, resistance to insulin action, and cardiovascular diseases later on." (PMID 32854204, 2020). "It is worth noting that the fasting insulin adjusted for BMI demonstrated the expected direction or correlation, suggesting that obesity influences the relationship between IMTmax and fasting insulin levels." (PMID 31801372, 2020). "Compared to lean individuals, people with overweight or obesity have increased fasting insulin levels, show sharp rises in insulin after carbohydrate consumption, and their postprandial insulin levels remain elevated for longer." (PMID 33007918, 2020). "To detect the effects of SEM on obesity-related metabolic disorders, we first examined the changes of insulin sensitivity in the obese mice." (PMID 31991934, 2020). "Experimental evidence suggests that obesity and T2DM are associated with increased activity of tyrosine phosphatase 1β (PTP1β), a negative regulator of the insulin signaling pathway." (PMID 32708368, 2020). "Increased brain insulin signaling sensitivity and reduced signs of anxiety and depression were observed in mice with diet-induced obesity treated with oral metronidazole or vancomycin." (PMID 32829453, 2020). "Elevated FFAs increase insulin secretion in the pancreas and decreases insulin sensitivity in the liver and muscle, which contributes to obesity-related metabolic complications." (PMID 31959221, 2020). "In this study, we observed that in patients with obesity and T2DM-Ins, bariatric surgery was associated with high rates of postoperative cessation of insulin therapy, which is, in turn, a major driver of overall reductions in direct healthcare cost." (PMID 33285553, 2020). "Accumulated lipids increase oxidative stress, and ROS produced in adipose tissue play an important role in obesity-related metabolic dysfunction, including insulin resistance." (PMID 33339396, 2020). "The LLE mice showed improved thermogenic activity, physical performance, and mitochondrial function, as well as resistance against the high-fat diet-induced obesity with elevated insulin sensitivity and subdued inflammation." (PMID 32639947, 2020). "An analysis of functional network built upon these genes points towards INS as a remarkable bridging factor connecting obesity and TC." (PMID 33240576, 2020). "SST and its analogues block the insulin secretion from pancreatic β-cell and seem, by all accounts, to be a promising agent to treat obesity." (PMID 32272767, 2020). "Exosomes released from adipocytes in obesity have been proposed to be involved in adipocyte/macrophage cross-talk and to affect insulin signaling." (PMID 32899117, 2020). "A mouse model of obesity induced by an HFD has been used to study obesity-related diseases, which are associated with fat accumulation, thermogenesis, insulin sensitivity, and glucose tolerance." (PMID 33274005, 2020). "Studies in rodents in which BAT is transplanted into diseased mouse models have shown that transplanted BAT improves insulin sensitivity, glucose metabolism, and obesity, likely mediated by batokine effects." (PMID 32158768, 2020).
Obesity (continued). "Additional studies are clearly warranted to decipher the link between obesity, metabolic complications and COVID-19 severity with specific attention to fat mass distribution, insulin resistance and inflammatory/immune profiles." (PMID 32472191, 2020). "Insulin stimulates lipogenesis and simultaneously inhibits lipolysis and storage of triglycerides which probably favours obesity." (PMID 33007918, 2020). "CLGI further promotes pancreatic beta cells injury, disturbance of insulin action, and induces glucose intolerance in obesity." (PMID 33276488, 2020). "HFD-induced obesity decreased basal and insulin-stimulated glucose uptake in VAT and SAT adipocytes relative to cells from ND animals." (PMID 32272860, 2020). "Obesity in aged individuals stimulates sarcopenia by altering skeletal muscle lipid metabolism, insulin resistance, and inflammatory pathways." (PMID 32508753, 2020). "Maturation of IL-18 by NLRP1 inflammasome prevents obesity and metabolic syndrome by increasing insulin sensitivity and peripheral FA uptake, but most commonly IL-1β masks the activity of IL-18 during systemic inflammation." (PMID 32143623, 2020). "Among these changes, the decreased GLUT4 expression in the membrane fraction of the frontal cortex suggested weaker insulin action only in the case of co-occurrence of depression and obesity." (PMID 31782099, 2020). "Myriocin also increased insulin-stimulated Akt phosphorylation in the liver and skeletal muscle in all of these obesity models." (PMID 32887221, 2020). "BM LNFP III positively contributed to infant height-for-age Z scores at 20 weeks and it seems to modulate metabolic pathways in mice, improving glucose tolerance, insulin sensitivity and suppressing liver lipogenesis in experimental model of obesity." (PMID 32793208, 2020). "Notoginsenosides can treat obesity by reducing lipid synthesis, inhibiting adipogenesis, promoting white adipose tissue browning, increasing energy consumption, and improving insulin sensitivity." (PMID 33841133, 2020). "After inducing obesity and observing impaired glycemic homeostasis, we assessed the serum inflammatory profile and the liver’s insulin sensitivity of the animals." (PMID 32847099, 2020). "Obesity is related to increases in the levels of insulin, insulin-like growth factor (IGF), and adipocyte-derived factors such as tumor necrosis factor (TNF)-alpha, leptin, and interleukin (IL)-6 and a decrease in levels of adiponectin." (PMID 32466596, 2020). "This study showed that radiotracer binding to 5-HTT in the diencephalon was lower in insulin-resistant individuals independently of body weight whereas hypothalamic 5-HTT binding was lower in individuals with obesity independently of insulin sensitivity." (PMID 33288788, 2020). "The miR-181b expression is found reduced in endothelial cells from the adipose tissue of a mouse model of obesity, suggesting a positive role in glucose homeostasis and insulin signaling." (PMID 32630452, 2020). "When treated with EGCG for 16 weeks, mice placed on a HFD and 10% fructose solution resisted obesity development and displayed better CNS insulin sensitivity than HFD-fed obese control mice." (PMID 33092099, 2020). "Another study has reported that IGFBP-1 concentrations are repressed in response to increased insulin levels in obesity, and that low IGFBP-1 concentrations forecast the development of T2D." (PMID 33905470, 2020). "In normal individuals, insulin upregulates leptin production to increase satiety when glucose levels are high; however, obesity induces leptin resistance, resulting in high blood leptin concentrations and high food intake." (PMID 33142995, 2020). "A. muciniphila has been proved to have a robust correlation with inflammatory markers and adipose tissue homeostasis, and also with insulin and glycemia at the onset of obesity." (PMID 32153527, 2020).
Obesity (continued). "This critical analysis also reveals that subcellular pools of specific DAG and ceramides species should be considered when analyzing insulin-resistant phenotypes in other contexts than obesity such as aging and physical inactivity." (PMID 32887221, 2020). "Convincing evidence shows the link between NAFLD, resistance to insulin and obesity with modification of histone such as demethylation of H3 at lys9." (PMID 32610503, 2020). "In this study, we investigated the role of the microbiota in regulating insulin clearance during diet-induced obesity." (PMID 32860984, 2020). "Genetic ablation of NLRP3 prevented obesity-induced inflammasome and caspase 1 activation in the liver as well as improved insulin sensitivity." (PMID 32992548, 2020). "In this regard, administration of NO2-OA to both genetic and dietary mouse models of obesity results in improved insulin sensitivity and glucose tolerance, as well as in protection against mitochondrial dysfunction." (PMID 33122195, 2020). "A previous study noted that the NOD-like receptor pyrin containing 3 (NLRP3) inflammasome is a culprit of obesity and IR and that obese Nlrp3-/- knockout (KO) mice are more insulin sensitive than obese wild-type mice." (PMID 32580621, 2020). "T2DM is characterized by four major metabolic abnormalities: obesity, impaired insulin action, insulin secretory dysfunction, and increased endogenous glucose output." (PMID 32397662, 2020). "The eighth k-means cluster (characterized primarily by obesity and insulin requirement) had patients represented in several different LCA groups with no one profile capturing more than 33% of the patients." (PMID 33306116, 2020). "In the view of above discussion, our results demonstrated that, in guinea pigs, persistent artificial light exposure increased the rate of insulin resistance and obesity by downregulating the AMPKα/PPARα signaling pathway." (PMID 33150187, 2020). "It is known that hyperglycemia is associated with a cascade of events which finally leads to endothelial disfunction, proinflammatory state, oxidative stress, atherosclerosis, alteration of insulin sensitivity and obesity." (PMID 32824505, 2020). "Obesity is a major health concern in many domesticated equids animals since it is related to metabolic abnormalities such as insulin dysregulation, hyperlipidaemia or laminitis." (PMID 32191712, 2020). "When obesity was induced by a high-fat diet, CDK5 and its associated PPARγ phosphorylation were upregulated in vivo, which led to impaired insulin sensitivity." (PMID 32054125, 2020). "Transgenic mice overexpressing PPARα in muscles develop glucose intolerance, and are insulin resistant even though they are protected from diet-induced obesity." (PMID 33137899, 2020). "They reported an odds ratio of 1.7 of being overweight in both males and females using anti-H1 compared to controls (95% CI, 1.23–2.31), thought to be due to the disruption of insulin and leptin signaling, leading to obesity." (PMID 33348647, 2020). "Mice fed on a high fat diet, or with genetic predisposition to obesity, show enormous elevation of SPP1 expression levels, while blocking SPP1 function by antibodies or genetic mutation improves insulin sensitivity." (PMID 33076817, 2020). "In this study, we found that administration of L. fermentum LM1016 suppressed diet-induced obesity and hepatic steatosis and improved serum metabolic markers, such as glucose, insulin, leptin, and cholesterol." (PMID 32917958, 2020). "Taken together, CSF-mediated changes in the intestinal microbiota were closely related to the improvements in host obesity and insulin sensitivity." (PMID 32013093, 2020). "Cardiovascular and metabolic health: This theme included keywords related to body mass index, obesity, blood pressure, insulin resistance, coronary heart disease, weight and birth weight." (PMID 32645067, 2020).